GRN (granulin precursor)
Diseases named in the same sentence as GRN in open-access papers (continued):
Sharing a sentence is not in itself a finding about the gene and the disease.
Cognitive impairment (19 papers, 2017 to 2025). Abnormal cognition is characterized by deficits in thinking, reasoning, or remembering. "CNV mutations in GRN exon 6 and exon 12 showed the strongest associations with cognitive impairment." (PMID 40725212, 2025). "A detailed statistical analysis of the different exons of the PSEN1, MAPT, and GRN genes in relation to the significantly associated cognitive impairment domains was conducted based on MoCA data." (PMID 40725212, 2025). "In AD mouse models, loss of GRN exacerbated plaque load and cognitive deficits, while lentiviral overexpression improved spatial memory and prevented hippocampal neuronal loss." (PMID 34366786, 2021). "Prior neuroimaging studies of FTD have associated executive dysfunction with frontal cortical GM disease but the current study suggests that such cognitive deficits in GRN mutation carriers are likely to be due to a complex combination of GM and WM disease." (PMID 31835286, 2019). "Other phenotypes have been associated with GRN mutations and include AD, PD, corticobasal syndrome, dementia with Lewy bodies, and mild cognitive impairment." (PMID 29370838, 2018). "According to the model–submodel test, CNV mutations in GRN exon 1 (p = 0.027) and exon 6 (p = 0.0029) may be associated with a specific cognitive impairment expressed by a MoCA abstract score." (PMID 40725212, 2025). "We used the Nucleic Acid Linked Immuno‐Sandwich Assay (NULISA) central nervous system panel for biomarker quantification in plasma, serum, and cerebrospinal fluid of patients with AD, mild cognitive impairment, Lewy body dementia, progranulin (GRN) mutation carriers." (PMID 40401628, 2025). "Moreover, proteins associated with cognitive impairments, like GRN, ARSA, NCAM1, and GUSB, also showed marked differences in protein levels." (PMID 32850779, 2020). "The results indicate that carriers of C9orf72seq, GRN, and MAPT mutations exhibit a significant global cognitive impairment compared to healthy controls." (PMID 40649976, 2025). "We identified associations with cognitive impairment specifically in the CNV mutations of the PSEN1 (exons 1, 9, 12), GRN (exons 1, 6, 12), and MAPT (exons 2, 8) genes." (PMID 40725212, 2025). "MAPT mutation carriers show lower scores on both MMSE and MoCA, with significant global cognitive impairment, although this is generally less severe than in GRN carriers." (PMID 40649976, 2025). "Several associations between CNV mutations in genes (APP, GRN, MAPT, PSEN1, PSEN2) and various domains of cognitive impairment were identified." (PMID 40725212, 2025). "In total, the cohort included 11 symptomatic heterozygous GRN mutation carriers (FTD-GRN; MC = mutation carrier), of which 3 patients were diagnosed with mild cognitive impairment (MCI) at the timepoint of CSF sampling." (PMID 37775827, 2023). "This could explain why MAPT mutation carriers do not exhibit the same breadth of cognitive impairments seen in C9orf72seq or GRN mutations." (PMID 40649976, 2025).
diabetes (18 papers, 2015 to 2025). "Such information is critical to therapies for GRN-deficient FTD, but also disease states in which GRN is upregulated or overexpressed, such as tissue injury, sepsis, diabetes and cancer." (PMID 40596721, 2025). "This study firstly revealed that neutrophil extracellular trap formation may represent the common biological processes of diabetes and stroke, and GRN may be potential intervention targets for T2DM-related stroke." (PMID 38166912, 2024).
Insulin resistance (18 papers, 2012 to 2023). Increased resistance towards insulin, that is, diminished effectiveness of insulin in reducing blood glucose levels. "Second, the progranulin (GRN) pathway, known to play a role in insulin resistance, was enriched in the PDDM group." (PMID 38082425, 2023).
systemic lupus erythematosus (18 papers, 2012 to 2025). An autoimmune multi-organ disease typically associated with vasculopathy and autoantibody production. "Taken together, these data indicated that serum GRN levels were up-regulated and were associated with the pathogenesis of LN in lupus mice." (PMID 23755248, 2013). "Serum GRN levels of lupus model were assayed by ELISA every 2 weeks and we found significantly increased serum GRN levels in lupus mice as compared with those in control mice 4 weeks after the initial ALD-DNA injection." (PMID 23755248, 2013). "The serum GRN levels were significantly elevated in pGRN-treated lupus mice compared with those in pcDNA3.1-treated lupus mice." (PMID 23755248, 2013). "Here, we carefully determined the potential role and possible mechanism of GRN in the pathogenesis of LN using ALD-DNA-induced lupus model." (PMID 23755248, 2013). "Decreased serum GRN levels were found in lupus mice injected with LV-shGRN versus those injected with LV-shNC." (PMID 23755248, 2013). "Serum creatinine levels were up-regulated in pGRN-treated lupus mice, indicating more sever LN by GRN overexpression." (PMID 23755248, 2013). "Exacerbation of renal pathology was found in the pGRN-treated lupus mice as compared with those controls, and the kidney score of pGRN-treated lupus mice was much higher than that of control mice, indicating severer LN resulted from GRN overexpression." (PMID 23755248, 2013). "For example, GRN assists in recruiting CpG oligonucleotides in macrophages by binding to Toll-like receptor 9 to exacerbate systemic lupus erythematosus severity, and GRN stimulates secretion of proinflammatory interleukin (IL)-8 by epithelial cells in multiple sclerosis." (PMID 36581897, 2022). "To study whether GRN was elevated in lupus model, we generated lupus mice according to our previously reported procedure." (PMID 23755248, 2013). "Consequently, these results demonstrated that GRN exacerbated LN in lupus model by promoting ALD-DNA-induced M2b polarization." (PMID 23755248, 2013). "To further confirm the modulation effect of GRN on the initiation and progression of LN, we then investigated whether down-regulation of GRN could ameliorate LN in lupus model." (PMID 23755248, 2013). "We further analyzed the kidney score and observed that LV-shGRN-injected lupus mice got lower kidney score compared with control mice, suggesting that down-regulation of GRN could ameliorate LN in lupus model." (PMID 23755248, 2013). "To investigate the effect of increased GRN on ALD-DNA-induced LN, we then analyzed renal pathology, kidney score and proteinuria in pGRN-treated or pcDNA3.1-treated lupus mice." (PMID 23755248, 2013). "On the other hand, in systemic lupus erythematosus (SLE), GRN (a degradation product of PGRN) may exacerbate immune responses and disease activity through its influence on TLR9 signaling." (PMID 41184265, 2025). "To test whether GRN could aggravate LN by enhancing ALD-DNA-induced M2b-polarized macrophages, we first isolated CD11b+/F4/80high renal macrophages from pGRN or pcDNA- 3.1-treated lupus mice, LV-shGRN or LV-shNC-injected lupus mice." (PMID 23755248, 2013).
tauopathy (18 papers, 2013 to 2025). Neurodegenerative disorders involving deposition of abnormal tau protein isoforms (tau proteins) in neurons and glial cells in the brain. "Biochemical features of accumulated tau in cases of GRN mutation (Case 3: lane 1, Case 4: lane 2) were compared with those of other tauopathies including CBD (lane 3), PSP (lane 4) and AD (lane 5) by immunoblot analysis of the sarkosyl-insoluble fraction using C-terminal tau antibody (T46)." (PMID 28473694, 2017). "Cases of GRN mutation may therefore represent a different tauopathy from that of AD, CBD, PSP and AGD." (PMID 28473694, 2017). "Surprisingly, this led to brains from GRN mutation carriers clustering closely with brains from MAPT mutation carriers, appearing to be more similar in expression profile than sporadic tauopathies." (PMID 36845551, 2023). "These gene signatures were largely specific for tauopathy; however, we identified a number of lysosomal genes that were altered in iPSC-neurons from MAPT mutations and in brains from GRN mutation carriers." (PMID 36845551, 2023). "We also identified other pathologies in our cohort, including PiD, FTLD-TDP type A associated with GRN mutations, and FTLD-TDP type B with AGD (a 4R tauopathy), which were all associated with +AOS." (PMID 34103532, 2021). "In a mouse model, tau hyperphosphorylation was significantly exacerbated due to reduced PGRN levels caused by mutations in GRN, demonstrating the role of PGRN in AD tauopathy." (PMID 35069175, 2021). "The FTDP-17 subtype associated with the MAPT mutation pathologically exhibits extensive tauopathy, while TDP-43–positive abnormal inclusions are the pathological hallmark in FTDP-17 associated with GRN mutations." (PMID 30518093, 2018). "The three major genes implicated in genetic FTLD are microtubule-associated protein tau (MAPT), progranulin (GRN) and chromosome 9 open reading frame 72 (C9orf72), where MAPT mutations are associated with a primary tauopathy and GRN and C9orf72 are associated with TDP-43 pathology." (PMID 38147792, 2024). "Small molecule therapies and tau monoclonal antibodies are also being developed for tauopathies (with a potential for use in MAPT mutations), and other options for GRN mutations include modification of proteins such as sortilin and HDAC that lead to increased GRN levels." (PMID 31119452, 2019). "One patient from the GRN+/A152T+ group received an additional diagnosis of unclassifiable tauopathy because in addition to FTLD-TDP A, tau burden was unusually diffuse and severe, with tau immunoreactivity found in astrocytes in a distribution that did not clearly fit a defined tauopathy." (PMID 28594853, 2017).
Brain atrophy (17 papers, 2013 to 2025). Partial or complete wasting (loss) of brain tissue that was once present. "Patients with GRN mutations often display asymmetric brain atrophy and parieto–occipital involvement, resulting in asymmetric visuospatial impairment and hemi-neglect, limb apraxia, and potentially CBS." (PMID 40722695, 2025). "This aligns with previous works demonstrating a faster progression rate of brain atrophy in individuals with pathogenic variants in GRN than those in C9orf72." (PMID 37609205, 2023). "This aligns with previous work demonstrating a faster progression rate of brain atrophy in individuals with pathogenic variants in GRN than those in C9orf72." (PMID 38062485, 2023). "In FTLD patients with GRN mutations, the pattern of brain atrophy was reported to be asymmetric and widespread, predominantly involving the frontal, inferior parietal, and posterior temporal cortices." (PMID 32184751, 2020). "In contrast, symmetric rates of brain atrophy were also found in symptomatic GRN mutation carriers in a longitudinal study." (PMID 32184751, 2020). "Indeed, mutations in GRN have been associated with faster rates of brain atrophy and more severe language impairment early in the course of the disease." (PMID 39766433, 2024). "Initially, in relation to GRN genetic mutation, it appears that individuals with bvFTD carrying GRN mutations demonstrate a faster rate of whole brain atrophy, suggesting a more rapid disease progression, compared to patients carrying other genetic variations, such as MAPT." (PMID 37762113, 2023). "Longitudinal data suggest that patients with pathogenic variants in GRN experience faster brain atrophy progression than those with pathogenic variants in C9orf72, indicating different rates of pathological progression and fundamental mechanisms associated with different gene variants." (PMID 37609205, 2023). "Brain atrophy is associated with elevated plasma markers in GRN carriers." (PMID 31620075, 2019). "These shared genes that are commonly expressed in regions more spared by cortical atrophy in C9orf72-bvFTD and GRN-bvFTD, and conversely, these genes are commonly expressed in regions more vulnerable to brain atrophy in MAPT-bvFTD." (PMID 39920674, 2025). "A recent study explored co-expression patterns associated with brain atrophy patterns in symptomatic FTD mutation carriers in C9orf72, GRN, and MAPT and report top 20 genes and relevant biological pathways." (PMID 38469573, 2024). "The metabolic changes appeared before brain atrophy on MRI and approximately more than 10 years before clinical onset, suggesting that FDG-PET changes can be detected as early biomarkers in GRN mutation carriers." (PMID 36051222, 2022). "Brain atrophy in presymptomatic carriers of common FTD mutations, including GRN, is affected by both genetic and environmental factors such as TMEM106B rs1990622 polymorphism." (PMID 29146050, 2018). "As a confirmation, glial fibrillary acidic protein (GFAP), a marker of astrogliosis, has been measured in several genetic mutations, including C9ORF72, GRN, and MAPT, and showed to be increased only in symptomatic GRN mutation carriers, correlating also with lower cognitive scores and brain atrophy." (PMID 37628709, 2023). "Conversely, shared genes with negative weights in C9orf72-bvFTD also displayed negative weights in GRN-bvFTD, suggesting that these genes were commonly expressed in regions more vulnerable to brain atrophy." (PMID 39920674, 2025).
ovarian carcinoma (17 papers, 2007 to 2025). A malignant neoplasm originating from the surface ovarian epithelium. "GRN has been described as a putative novel growth factor for ovarian cancer, and was found to be highly secreted by ovarian cancer cells." (PMID 19936259, 2009). "GRN has been characterized as a prognostic marker in ovarian cancer." (PMID 25110883, 2014). "Liu9 tested the expression level of GRN in three types of human ovarian cancer cell lines with different malignant potentialities and demonstrated that the expression level of GRN was closely and positively correlated with tumor cell proliferation and invasiveness." (PMID 24349832, 2013). "Increased levels of GRN and RARRES2 in plasma from ovarian cancer patients in both the early and the late stage cases are a novel findings in this study." (PMID 19936259, 2009). "The EGFR‐COPA/GRN/HBEGF pairs were expressed at higher levels in the metastatic tumors than those in the primary tumors, suggesting that these cell‐to‐cell connections might be important for ovarian cancer metastasis." (PMID 34459128, 2021).
hepatocellular carcinoma (16 papers, 2009 to 2025). A malignant tumor that arises from hepatocytes. "The GRN gene was repressed in Hep3B hepatoma cells by different editors, including dCas9-DNMT3a, dCas9-EZH2, and dCas9-KRAB." (PMID 40650152, 2025). "For example, Chiou and colleagues successfully used these data to identify S100A9 and GRN as combinatorial biomarkers for early identification of hepatocellular carcinoma (HCC) from urine." (PMID 37168844, 2023). "The authors used dCas9-KRAB to epigenetically target GRN in hepatic carcinoma cells and demonstrated its effect on Hep3B carcinoma cells." (PMID 37873808, 2023). "In the present study, we found that GRN A displayed potent anticancer effect in vivo; treatment of the mice bearing hepatocellular carcinoma HegG2 cancer cells with GRN A resulted in a significant inhibitory effect on tumor growth." (PMID 30301274, 2018). "Increased GRN expression is observed in many neoplasias, especially in hepatocellular carcinoma." (PMID 37873808, 2023). "Our results confirmed that GRN A enhances the inhibitory effect of cisplatin significantly; treatment of the hepatocellular carcinoma with the combination of GRN A and cisplatin leads to more potent inhibitory effect on cancer cells growth, as analyzed by apoptosis and colony formation assay." (PMID 30301274, 2018). "GRN-overexpressed hepatocellular carcinoma (HCC) cells had stem cell-like properties, and patients with GRN-overexpressed HCC had a poor prognosis." (PMID 28211531, 2017).
Sepsis (16 papers, 2018 to 2025). Sepsis is defined as life-threatening organ dysfunction caused by a dysregulated host response to infection. "For example, many studies have shown that GRN signaling plays an essential role in sepsis immunity, including bacterial clearance, cell growth and survival, tissue repair, and the regulation of inflammation." (PMID 35634310, 2022). "However, GRN signaling was classified into different groups, suggesting differential effects of GRN signaling in septic shock versus sepsis." (PMID 36304125, 2022). "We specifically examined how GRN communications change between sepsis and septic shock." (PMID 36304125, 2022). "Comparing the signaling pathways in these two groups, it can be seen that all three pathways, GRN,CCL, and PARs, are specifically expressed in the COVID-19-associated ARDS, while BAFF, CXC, LRESITIN, CypA, and MIF are specifically expressed in the sepsis-related ARDS." (PMID 38745657, 2024). "This network demonstrated an upregulating effect of miR-125b-5p on SORT1 and GRN, and identified vascular endothelial growth factor A (VEGFA) as a possible target of GRN in sepsis." (PMID 34476621, 2021). "In 26 upregulated OCRGs in AIs, the upregulation of two regulators, SERPINA1 and AZU1, was shared among acute respiratory distress syndrome (ARDS), sepsis, and trauma; upregulation of CD24 and FKBP8 was shared among ARDS and trauma; and upregulation of GRN was shared between sepsis and trauma." (PMID 34368262, 2021).
motor neuron disease (15 papers, 2009 to 2026). "Rarely, GRN mutations present as motor neuron disease, corticobasal syndrome or progressive supranuclear palsy." (PMID 34366786, 2021). "Since GRN mutations are associated with FTD-TDP pathology, which is frequently observed also in ALS and FTD-ALS, it prompted the search for GRN mutations in patients with associated motor neuron disease." (PMID 26388768, 2015). "On the contrary, when AOS accompanies behavioral dyscontrol, executive dysfunction, or features of motor neuron disease, the underlying pathology is heterogeneous, less commonly 4R tau, and may be related to a mutation in the GRN gene." (PMID 34103532, 2021). "Among its clinical variants, the behavioral variant (bvFTD) is the most frequently inherited, often associated with mutations in MAPT, GRN, and C9ORF72, the latter being the most prevalent genetic cause of FTD and FTD-motor neuron disease (FTD-MND)." (PMID 41500252, 2026). "In Creutzfeldt–Jakob disease, motor neuron disease, and AD, GRN expression is increased in activated microglia." (PMID 38291418, 2024). "In a mouse model of motor neuron disease, increased microglial GRN expression marked the degenerative process." (PMID 34366786, 2021).
corticobasal syndrome (14 papers, 2016 to 2025). Corticobasal syndrome (CBS) is a rare neurodegenerative disease characterized by multifaceted motor system dysfunctions and cognitive defects such as asymmetric rigidity, bradykinesia, limb apraxia, and visuospatial dysfunction. "The GRN c.708+1G>A variant was previously reported in several FTD, FTLD, and corticobasal syndrome (CBS) cases, mostly early-onset." (PMID 39606324, 2024). "Heterozygous mutations in the progranulin gene (GRN) are one of the most frequent causes of inherited frontotemporal dementia (FTD), presenting with behavioral variant FTD, primary progressive aphasia, or corticobasal syndrome phenotypes." (PMID 39614734, 2025).